KLRB1 (killer cell lectin like receptor B1)
Description:
Plays an inhibitory role on natural killer (NK) cells cytotoxicity. Activation results in specific acid sphingomyelinase/SMPD1 stimulation with subsequent marked elevation of intracellular ceramide. Activation also leads to AKT1/PKB and RPS6KA1/RSK1 kinases stimulation as well as markedly enhanced T-cell proliferation induced by anti-CD3. Acts as a lectin that binds to the terminal carbohydrate Gal-alpha(1,3)Gal epitope as well as to the N-acetyllactosamine epitope. Also binds to CLEC2D/LLT1 as a ligand and inhibits NK cell-mediated cytotoxicity as well as interferon-gamma secretion in target cells.
Synonyms: NKR-P1A; CD161; CLEC5B; NKRP1A; NKR-P1; hNKR-P1A; NKR
Tractability: Antibody: its Gene Ontology location is reachable by antibodies, with high confidence; UniProt predicts a signal peptide or a membrane-spanning region. PROTAC: its protein half-life has been measured.
Gene: Protein-coding gene on chromosome 12 (9,594,551 to 9,607,916, reverse strand). Ensembl gene ENSG00000111796.
Subcellular location: Membrane
Subcellular location (Human Protein Atlas): Nucleoplasm; Cytosol
Pathways (Reactome):
Immune System: Immunoregulatory interactions between a Lymphoid and a non-Lymphoid cell
Gene Ontology:
Molecular function: protein binding; carbohydrate binding; signaling receptor activity; transmembrane signaling receptor activity
Biological process: cell surface receptor signaling pathway; regulation of natural killer cell mediated cytotoxicity
Cellular component: cell surface; plasma membrane; membrane
Genetic constraint (gnomAD): Loss-of-function variants: 8 observed, 15.17 expected, observed/expected ratio (o/e) 0.53, 90% interval 0.31 to 0.95. The upper end of that interval is the gene's LOEUF score, 0.95, which puts it in group 4 of 6, group 1 being the genes least tolerant of losing a copy. Missense variants: 124 observed, 142.41 expected, observed/expected ratio (o/e) 0.87, 90% interval 0.75 to 1.01. Synonymous variants: 45 observed, 55.48 expected, observed/expected ratio (o/e) 0.81, 90% interval 0.64 to 1.04.
Homologues: Orthologues: chimpanzee KLRB1 (99% identical), macaque KLRB1 (87% identical), dog KLRB1 (63% identical), pig KLRB1 (62% identical), mouse Klrb1 (47% identical), mouse Klrb1a (47% identical), mouse Klrb1c (47% identical), rat Klrb1 (46% identical), rat Klrb1b (46% identical), mouse Klrb1b (44% identical), mouse Klrb1f (44% identical), rat Klrb1c (44% identical), and 6 more. Paralogues in human: CLEC7A (24% identical), CLEC12B (22% identical), KLRF1 (22% identical), CLEC9A (22% identical), KLRC1 (21% identical), KLRG1 (21% identical), KLRC2 (20% identical), KLRF2 (20% identical), OLR1 (20% identical), KLRC3 (20% identical), CLEC12A (20% identical), KLRD1 (19% identical), and 11 more.
Diseases named in the same sentence as KLRB1 in open-access papers:
KLRB1 is named in the same sentence as 207 diseases in open-access papers, as found by Europe PMC text mining. Sharing a sentence is not in itself a finding about the gene and the disease. The quoted sentences say what the papers report.
glioma (29 papers, 2019 to 2026). A benign or malignant brain and spinal cord tumor that arises from glial cells (astrocytes, oligodendrocytes, ependymal cells). "Knockdown of KLRB1, the gene encoding CD161, strongly enhanced the ability of T cells to attack glioma cells and reduced T cell exhaustion." (PMID 38165493, 2024). "In gliomas, an important receptor is natural killer receptor protein 1 (CD161), which is encoded by the KLRB1 gene (“Killer Cell Lectin Like Receptor B1 gene”) and acts as a suppressor of T cell cytotoxicity and NK cell activity." (PMID 38275375, 2023). "Researchers found that CD161 can suppress T cell anti-tumor immunity in glioma, and knocking down KLRB1 or using an antibody-mediated blockade of CD161 can enhance the ability of T cells to kill tumors." (PMID 40115278, 2025). "CD161, which is encoded by killer cell lectin-like receptor subfamily B member 1 (KLRB1), has recently been proposed as a potential inhibitory receptor and a promising novel target for immunotherapeutic treatments of glioma." (PMID 40115278, 2025). "For instance, high expression of KLRB1 has been shown to promote the progression and evolution of gliomas by influencing T cell dysfunction." (PMID 39202452, 2024). "KLRB1 (encoding CD161) has been reported as an inhibitory receptor for glioma immunotherapy, whose blockade will enhance T cell-mediated killing of glioma cells both in vitro and in vivo experiments." (PMID 37056564, 2023). "The development of immune targets, including programmed cell death 1 (PD1), cytotoxic T lymphocyte-associated protein 4 (CTLA4), and killer cell lectin-like receptor subfamily B member 1 (KLRB1), lays the groundwork for further tumor-free treatment of glioma." (PMID 37476838, 2023). "Studies have shown that KLRB1 gene inactivation enhances T-cell-mediated killing of glioma cells in vitro and the anti-tumor function of KLRB1 in vivo, whereas decreased KLRB1 expression has been associated with poor prognosis in BC patients." (PMID 37988189, 2023). "A single-cell RNA-seq study of patient glioma infiltrating T cells revealed CD161 (KLRB1) as a promising immunotherapy target." (PMID 38239396, 2023). "A new study suggests that KLRB1 gene inactivation or antibody-mediated KLRB1 blockade strengthens T cell-mediated killing of glioma cells in extracorporal and their antitumor function in vivo." (PMID 36660546, 2022). "Inactivation of KLRB1 gene in T cells transferred in the brain of glioma-bearing mice slowed down tumor growth." (PMID 35185935, 2022). "KLRB1 gene inactivation or antibody-mediated KLRB1 blockade enhances T cell-mediated glioma cell killing in vitro, and the CD161_CLEC2D pathway defines a potential target for immunotherapy of glioma and other human cancers." (PMID 37818360, 2023). "In the PBMC compartment of patients we also observed KLRB1 (CD161), which was recently discovered as a functional marker on human CD8+ T cells in the TME of glioma." (PMID 36796366, 2023). "They performed RNAseq analysis of TILs from resected gliomas and identified highly cytotoxic CD8+ T cells expressing KLRB1, as well as conventional CD4+ T cells." (PMID 35185935, 2022). "recently revealed that glioma-infiltrating CD8+ T-cells with high cytotoxicity expressed several NK cell markers, including KLRB1 (CD161) by scRNA-seq." (PMID 36081501, 2022). "Furthermore, we also examined the expression of several other key genes associated with immune regulation in different groups, including KLRB1, CD70, and FASLG, which have been shown to play key roles in glioma immune evasion." (PMID 38971948, 2024). "Moreover, we observed significant interactions between KLRB1 (Tc) and CLEC2D (mBc1-4), which has recently been described to inhibit killing of glioma cells by T cells." (PMID 36153593, 2022).
breast carcinoma (21 papers, 2018 to 2026). "Using this data, we constructed a risk prediction model to predict breast cancer prognosis and evaluated the correlation between KLRB1 expression and clinicopathological features and immune invasion." (PMID 37351109, 2023). "This study explored the potential value of KLRB1 as a breast cancer (BC) biomarker and its close association with the tumor immune microenvironment during the development of BC." (PMID 37520246, 2023). "Considering that KLRB1 expression correlates with the molecular typing of breast cancer, we further analyzed and found that KLRB1 was also associated with the prognosis of Luminal A and Luminal B subtypes, but not statistically significant with HER-2 positivity and TNBC survival." (PMID 37351109, 2023). "KLRB1 may be a potential prognostic marker and therapeutic target associated with the microenzymic environment of breast cancer tumors, providing a new direction for breast cancer treatment." (PMID 37351109, 2023). "Previous investigations have employed machine learning algorithms for molecular subtyping and prognostic model construction in breast cancer, identifying CRTAM, CLEC2D, and KLRB1 as pivotal hub genes associated with exhausted CD8+ T cell phenotypes." (PMID 40994935, 2025). "Paired breast cancer tissue analysis confirmed that KLRB1 expression was significantly lower in tumors compared to adjacent normal tissues." (PMID 40612672, 2025). "Survival analysis using the Kaplan-Meier Plotter database further demonstrated that higher KLRB1 expression was associated with significantly better OS and RFS in HR+ breast cancer patients." (PMID 40612672, 2025). "H&E staining further validated that breast cancer tissues with high KLRB1 expression exhibited increased lymphocyte infiltration." (PMID 40612672, 2025). "Recent studies in tumor immunology-related prognostic models indicate that KLRB1 is a crucial gene affecting the prognosis of lung adenocarcinoma, liver cancer, and breast cancer." (PMID 40956822, 2025). "In our analysis, KLRB1 was found to be downregulated in breast cancer while being abundantly expressed in CD8+ T cells." (PMID 39202452, 2024). "Further analysis through KM survival analysis and univariate and multivariate Cox regression analysis demonstrated that KLRB1 is an independent prognostic factor for breast cancer." (PMID 37351109, 2023). "Then we demonstrated that the KLRB1 protein is significantly lower than normal breast epithelial cells in breast cancer MCF7 and MDA-MB-231 cells." (PMID 37351109, 2023). "KLRB1 was also found to inhibit the proliferation of breast cancer cells by blocking cell division in the G1/M phase." (PMID 37351109, 2023). "Relationships between KLRB1 expression and clinical characteristics in breast cancers using chi-square and Fisher’s exact tests." (PMID 37520246, 2023). "Increased KLRB1 expression levels were correlated with inhibition of breast cancer cell proliferation, migration, and invasion, as well as promotion of cell apoptosis, possible through regulation of the NF-κB, PI3K/AKT, and TNF signaling pathways." (PMID 37988189, 2023). "The KLRB1 is closely related to age, clinical stage, pathological type, estrogen receptor and molecular typing of breast cancer." (PMID 37351109, 2023). "Univariate and multivariate analyses of the correlations of KLRB1 expression with RFS in breast cancer patients." (PMID 37520246, 2023). "Univariate and multivariate analyses of the correlations of KLRB1 expression with OS in breast cancer patients." (PMID 37520246, 2023). "A series of studies on prognostic signatures related to tumor immunity have pointed out that KLRB1 is a crucial gene affecting prognoses in lung adenocarcinoma, liver cancer, and breast cancer." (PMID 35028320, 2022). "Then based on the median expression levels of CD2, ZNF683 and KLRB1 separately, the breast cancer patients were divided into high-expressed subgroups and low-expressed subgroups." (PMID 36090993, 2022).
breast carcinoma (continued). "A bioinformatics study reveals that the up-regulation of KLRB1 (a TME-associated and immune-related signature) is correlated with favorable survival in breast cancer patients." (PMID 36090993, 2022). "Our results also confirmed that patients with higher expression of KLRB1 achieve longer survival in different cancers including breast cancer, melanoma, and thyroid cancer." (PMID 35028320, 2022). "A previous pan-cancer study also confirmed that upregulation of KLRB1 was related to good prognosis in most cancers, including breast cancer." (PMID 36243728, 2022). "Additionally, mIHC analysis demonstrated that KLRB1 expression was higher in HR+ breast cancer patients with a low LMF_index, and patients with high KLRB1 expression also exhibited elevated PD-L1 levels." (PMID 40612672, 2025). "Furthermore, in breast cancer molecular subtypes, KLRB1 and KLRK1 were higher in TNBC and ER+/HER2+BC in contrast to ER+/HER2−BC." (PMID 38713229, 2024). "Finally, in vitro experiments confirmed that overexpression of KLRB1 inhibits breast cancer cell proliferation, migration, invasion, and DNA replication ability." (PMID 37351109, 2023). "Additionally, we investigated the role of KLRB1 in breast cancer using various experimental techniques including real-time quantitative PCR, MTT assays, Transwell assays, Wound healing assays, EdU assays, and flow cytometry." (PMID 37351109, 2023). "Then we found that KLRB1 was strongly associated with DSS and PFI in breast cancer." (PMID 37351109, 2023). "Another gene with significance in overall survival for patients with PP breast cancer is KLRB1." (PMID 36675137, 2023). "We also assessed baseline data on high and low expression of KLRB1 in breast cancer." (PMID 37351109, 2023). "An AA metabolic signature (SPINK8, KLRB1, APOD and PIGR) was constructed for breast cancer prognosis." (PMID 36243728, 2022). "In order to characterize whether these genes are regulated by methylation levels, we downloaded illumina methylation 450 K beadChip data of 890 breast cancer samples from TCGA project, and 4 genes (PXDNL, SLC27A2, KLRB1 and IGHV1-12) were detected." (PMID 36869083, 2023).
COVID-19 (21 papers, 2020 to 2026). A disease caused by infection with severe acute respiratory syndrome coronavirus 2. "In contrast, the expression of genes CACNA2D3 and KLRB1 has decreased in severe COVID-19 patients." (PMID 38262689, 2024). "Both, severe and mild COVID-19 in comparison to controls shared neutrophil-specific CD177 and HP expression among the most upregulated DEGs, as well as lymphocyte-associated genes such as ABLIM1, NELL2, RCAN3, RORC, BACH2, and KLRB1, among the downregulated genes." (PMID 33441124, 2021). "Results revealed a negative correlation between neutrophils and CD247, CD2, and KLRB1, and a positive correlation with RETN in both COVID-19 and sepsis." (PMID 37822934, 2023). "Of these, six hub genes (CD247, CD2, CD40LG, KLRB1, LCN2, RETN) showed significant alterations across COVID-19, sepsis, and geriatric sepsis-induced ARDS." (PMID 37822934, 2023). "Currently, there was not much research on KLRB1 gene, which also offered a new idea for targeted treatment of diseases in COVID-19." (PMID 35464423, 2022). "In addition to robust cytotoxic T cell functions, enrichment of KLRB1, GZMA, and GZMK transcripts may indicate enhanced NK cell cytotoxic activity in Δ382 SARS-CoV-2 infected patients, in which the function is impaired in severe COVID-19 patients." (PMID 34716845, 2022). "CD247, CD2, CD40LG, and KLRB1 displayed a positive correlation with CD8+ T cells and CD4+ T cells in both COVID-19 and sepsis cases, while LCN2 and RETN showed a negative correlation." (PMID 37822934, 2023). "In addition, GSEA analysis identified a negative relationship between KLRB1 and CD1C expression and the severe phenotype of COVID-19 patients." (PMID 38262689, 2024).
autoimmune disease (19 papers, 2011 to 2025). A disorder resulting from loss of function or tissue destruction of an organ or multiple organs, arising from humoral or cellular immune responses of the individual to their own tissue constituents. "Apart from SLE, aberrant KLRB1 expression has been correlated with other autoimmune diseases and inflammatory responses, including rheumatoid arthritis (RA), multiple sclerosis (MS), and sepsis." (PMID 38774864, 2024). "The exact mechanism remains unclear, but KLRB1 may develop into a biological marker specific to autoimmune diseases in the future." (PMID 38774864, 2024).
rheumatoid arthritis (19 papers, 2013 to 2025). A chronic, systemic autoimmune disorder characterized by inflammation in the synovial membranes and articular surfaces. "KLRB1 has been previously shown to be downregulated in rheumatoid arthritis and SLE." (PMID 34435051, 2021).
psoriasis (16 papers, 2011 to 2025). An autoimmune condition characterized by red, well-delineated plaques with silvery scales that are usually on the extensor surfaces and scalp. "These correlations provide insights into the interactions between FABP5, KLRB1, and T cells, contributing to our understanding of the underlying immunological mechanisms in psoriasis and the effects of different therapeutic interventions." (PMID 38596682, 2024). "Tofacitinib demonstrates advantages in studying drugs targeting DCs, with elevated expression and co-localization of FABP5 and KLRB1 in psoriasis." (PMID 38596682, 2024). "To validate these findings, we performed gene expression analysis of scRNA-seq data, which confirmed the overexpression of FABP5 and KLRB1 in cluster 1 DCs, reinforcing their potential role in psoriasis." (PMID 38596682, 2024). "In psoriasis patients, KLRB1 exhibited heightened expression in the stratum corneum and dermis, while FABP5 showed increased expression in the entire dermis and epidermis, as indicated by brownish-yellow coloration in corresponding immunohistochemistry images." (PMID 38596682, 2024). "To explore the correlation between FABP5 and KLRB1, we examined skin lesions from three psoriasis patients and three healthy controls using immunofluorescence double staining." (PMID 38596682, 2024). "To investigate the relationship between FABP5, KLRB1, and T cells in psoriasis, we performed Pearson’s correlation analysis using data from a psoriasis cohort." (PMID 38596682, 2024). "FABP5 alone lacks specificity as a biomarker for psoriasis, but its combination with KLRB1 enables differentiation from other skin diseases." (PMID 38596682, 2024). "Quantitative analysis further demonstrated a statistically significant elevation in FABP5 positivity (55.47 vs. 33.24) and KLRB1 positivity (14.30 vs. 9.932) in the psoriasis group (p-values 0.0253 and 0.0211, respectively)." (PMID 38596682, 2024). "The results demonstrated that FABP5 and KLRB1 were significantly upregulated in psoriasis skin tissues." (PMID 38596682, 2024). "FABP5 positivity coupled with KLRB1 negativity was observed at 40.56 in the psoriasis group and 11.91 in the normal group, while KLRB1 positivity with FABP5 negativity stood at 18.33 in the psoriasis group and 7.542 in the normal group." (PMID 38596682, 2024). "The substantial evidence suggests an elevation in FABP5 and KLRB1 expression in psoriasis, with a more pronounced trend in FABP5 than in KLRB1." (PMID 38596682, 2024). "Double positivity for FABP5 and KLRB1 was 14.91 in the psoriasis group and 2.389 in the control group, exhibiting a slightly lower yet statistically more significant tendency for elevation than the first two groups (p-value 0.0024)." (PMID 38596682, 2024). "Additional investigations are needed to explore the relationship and mechanisms of action between FABP5 and KLRB1 in psoriasis." (PMID 38596682, 2024). "To further verify the predictive effect of FABP5 and KLRB1, we conducted differential expression analysis in two independent psoriasis cohorts." (PMID 38596682, 2024). "Combined with the analysis of fluorescence intensity curves, we deduce a co-localization of KLRB1 and FABP5 in both psoriasis and normal skin tissues, elucidating the characteristics of KLRB1 and FABP5 in these contexts." (PMID 38596682, 2024). "Semi-quantitative analysis revealed an average positively stained area of 0.5016 for KLRB1 in the psoriasis group, compared to 0.1971 in the normal group." (PMID 38596682, 2024). "The downstream pathways of FABP5 vary across various dermatologic diseases, and our team’s future research will concentrate on the detailed mechanistic examination of FABP5 and KLRB1 in psoriasis." (PMID 38596682, 2024). "In two patients with difficult-to-treat types of psoriasis, we observed both IL-17A and IL-17F-producing KLRB1+ cells." (PMID 33329560, 2020). "The double positive of FABP5 and KLRB1 has higher specificity in the psoriasis group." (PMID 38596682, 2024).